CD81 (CD81 molecule)
Diseases named in the same sentence as CD81 in open-access papers (continued):
Sharing a sentence is not in itself a finding about the gene and the disease.
infection (continued). "Anti-CD81 mAbs inhibit Luc-Jc1 infection of Huh7.5.1 cells in a dose-dependent manner (IC50 of 0.7–8 μg/ml)." (PMID 23704981, 2013). "The kinetics of infection inhibition with anti-SR-BI- and anti-CD81-Abs suggest that SR-BI is involved in virus/cell recognition upstream of the CD81 interaction." (PMID 22069522, 2011). "When cells with a log-normal distribution of the CD81 expression level were exposed to virions in vitro, we found that infection proceeded in three phases." (PMID 22174670, 2011). "Albeit of human hepatic origin, the HepG2 cell line lacks CD81 and is poorly permissive for HCV entry but can be rendered permissive by CD81 expression, as previously shown by infection with HCVpp or HCVcc." (PMID 21533214, 2011). "Viral RNA and HCV proteins were detected 4 days post inoculation and the infection occurred in a CD81-dependent manner." (PMID 21887279, 2011). "In effect, we assumed that the differences in the viral clones, JFH-1 and Jc1, and the cell lines, Huh7.5 and the combination of Huh7-Lunet and Lunet/CD81, affected the viral production rate and/or the infection rate." (PMID 22174670, 2011). "The virion particles associated with the CD81-Fc-conjugated resin and the HCV RNA entered into Huh7.5.1 after infection was drastically reduced by the incubation of virus stocks at 37°C." (PMID 21829654, 2011). "To analyze the influence of these amino acid changes on RNA-replication, virus production and infection of cells expressing human or mouse CD81, we transferred them individually or in combinations into the backbone of Jc1." (PMID 20617177, 2010). "Similar to the mouse ortholog, infection through rat and hamster CD81 was approximately 100-fold more efficient with Jc1/mCD81 compared to parental Jc1." (PMID 20617177, 2010). "To this end we stably overexpressed CD81 in the HepG2(N6) cell line, which displays simple columnar polarity, to render these cells permissive to HCVcc and HCVpp infection." (PMID 20949066, 2010). "Second, we quantified the threshold level of human CD81 needed for productive infection of Huh7-Lunet cells." (PMID 20617177, 2010). "In this study we took advantage of a human liver cell line expressing mouse in place of human CD81 to select for a population of HCV that utilizes this entry factor with high efficiency for infection of host cells." (PMID 20617177, 2010). "Antibody to CD81 prevented infection by this HJ3-5(KR) virus, suggesting that it enters cells via the well characterized HCV receptor mechanism (data not shown)." (PMID 20824094, 2010). "Using this approach the relation between CD81 cell surface level and infection efficiency can be quantified using a dual colour FACS analysis." (PMID 20617177, 2010). "To address if these mutations specifically permit infection via mouse CD81 or if they would also increase HCV infection through CD81 from other rodent species, we cloned rat and hamster CD81 and stably transduced Lunet N cells with these orthologs." (PMID 20617177, 2010). "Infection of primary human hepatocytes or hepatoma cell lines was inhibited by anti CD81 antibodies and after downregulation of CD81 using an siRNA approach." (PMID 21994653, 2010). "This increase was detected as early as 6 hrs after infection for Huh7.25/CD81 cells and 10.5 hrs for Huh7.5 cells, with a maximum expression at 12 hrs for both cell types." (PMID 20485506, 2010). "Here we report the use of HCV permissive Huh7.25.CD81 cells to analyse the effect of HCV on the RIG-I/MAVS-mediated IFN induction pathway during the early hours after infection, before the HCV NS3/4A protease can cleave MAVS and abrogate this pathway." (PMID 20485506, 2010). "The effective interaction of the HCV glycoproteins, SRBI, and CD81 are necessary for a productive infection to occur." (PMID 19643019, 2009).
infection (continued). "In our study, infection of Huh-7 target cells with highly infectious HCVcc particles allowed us to isolate a cellular clone resistant to HCV infection which has lost CD81 expression (Huh-7w7 cells)." (PMID 19476617, 2009). "In light of these results, we transiently transfected Huh7-4 and -8 cells as well as Huh7-6 cells with vectors expressing human CD81 or SR-B1, respectively, and reassessed their permissiveness for HCVpp infection 48 h post-transfection." (PMID 19668344, 2009). "These cells therefore represent an alternative model to study the molecular determinants of CD81 that play a role in the infection of hepatocytic cells by P. yoelii sporozoites." (PMID 18389082, 2008). "The aim of this study was to uncover the residues of CD81 that are critical for host cell infection by sporozoites." (PMID 18389082, 2008). "Here we have characterized CD81 molecular determinants required for infection of hepatocytic cells by P. yoelii sporozoites." (PMID 18389082, 2008). "In contrast, our results indicate that the A–B region of CD81 on a CD9 backbone is sufficient to allow infection of hepatocytic cells by P. yoelii sporozoites." (PMID 18389082, 2008). "The infection rate of cells expressing CD81ccg9 was about half that of CD81-expressing cells, despite a higher level of expression as determined by flow-cytometry (data not shown)." (PMID 18389082, 2008). "Similar intracellular structures have been recently described in HIV infected macrophages, which concentrate virions in CD81-positive, plasma membrane-derived intracellular invaginations during productive infection." (PMID 18725936, 2008). "The surface expression and the conformation of the CD81 mutants unable to support infection by P. yoelii sporozoites were tested." (PMID 18389082, 2008). "Efforts to identify additional CD81 partner molecules will provide insights into the mechanisms by which CD81 supports infection by Plasmodium sporozoites." (PMID 18389082, 2008). "We have here studied the regions of CD81 that are important for infection, by exchanging segments with the corresponding parts of a closely related molecule, or by mutating discrete residues." (PMID 18389082, 2008). "On the hepatocyte side, the only surface protein known to play a key role in the infection by several Plasmodium species is the tetraspanin CD81." (PMID 18389082, 2008). "In a second step, following an analysis of CD81 crystal structure, and previous modelling studies, we identified several residues of a solvent-exposed region that are critical for infection." (PMID 18389082, 2008). "The CD9/CD81 chimeras containing CD81 B helix but in which the C helix was that of CD9 (CD81ccg9 and CD9[81B]) had a reduced ability to support infection by P. yoelii sporozoites as compared to WT CD81." (PMID 18389082, 2008). "So far, only one host molecule, the tetraspanin CD81, has been shown to play a crucial role in the infection by several Plasmodium species, including P. falciparum, the deadliest human parasite." (PMID 18389082, 2008). "A chimera in which a CD81/CD9 sequence switch was made just before the beginning of the D helix (CD81ABC-9DE) was as efficient as CD81 in supporting infection by P. yoelii sporozoites when expressed in HepG2-A16 cells." (PMID 18389082, 2008). "The level of infection in HepG2-A16 cells expressing these constructs was intermediate between the levels obtained after expression of CD81 and CD81ccg9, respectively." (PMID 18389082, 2008). "CD81 and SR-B1 are essential for hepatocyte infection by P. falciparum and P. vivax, respectively." (PMID 41411280, 2025). "Similarly, it was previously shown that the treatment of cells with antibodies specific for the Tspans CD9, CD63, and CD81 reduced the infection by the coronavirus MHV and SARS-CoV, MERS-CoV, and HCoV-229E pseudovirus transductions in susceptible cells." (PMID 40872854, 2025).
infection (continued). "Furthermore, CD81 has been demonstrated to be involved in the infection processes of various viruses, including influenza A virus, human immunodeficiency virus, and herpes simplex virus type 1, among others (29, –, 31)." (PMID 39745447, 2025). "Furthermore, because all studies were conducted using ex vivo infected cells, additional work on role of CD81 in the early and late phases of Mab infection should be carried out using mouse models of infection." (PMID 36818301, 2023). "The virus uses CD81 as a rheostat to control different stages of the infection via interaction with different proteins such as EWI-2, but also the deoxynucleoside triphosphate phosphohydrolase SAMHD1 (sterile alpha motif and histidine aspartic acid domain containing protein 1)." (PMID 37046846, 2023). "Notably, the HIV-1 virus uses CD81-lined vesicle structures to infect astrocytes, and then these energy-consuming glial cells support trans-infection of HIV-1 to T-cells." (PMID 37046846, 2023). "Because the present work focused essentially on Mab, it would be relevant to explore whether other pathogenic mycobacteria, including M. tuberculosis, are also dependent on CD81 during the early interaction and infection with macrophages." (PMID 36818301, 2023). "Expression of CD81 increased the EGFP signal 24 h post-CHIKV VRP infection by 3- to 4-fold." (PMID 35612284, 2022). "Importantly, CD81 is dispensable for infection with coronaviruses and arenaviruses tested in this study, demonstrating that CD81 is an alphavirus-specific replication factor." (PMID 35612284, 2022). "However, upon CD81 expression, cells became highly permissive (31% versus 0.3% and 94% versus 4% compared to parental cells) at a multiplicity of infection (MOI) of 1 and 10, respectively." (PMID 35612284, 2022). "To investigate whether CD81 is a human-specific CHIKV host factor, we evaluated whether overexpression of murine CD81 (mCD81) also enhances infection of CHIKV LR2006-OPY1 in Lunet N#3 cells (Lunet N#3 mCD81)." (PMID 35612284, 2022). "Additionally, infection with HCV-JFH1-based HCVpp having M706L mutation, similar to that with wild-type HCV-JFH1-based HCVpp, showed a CD81-, SRBI-, and OCLN-dependent manner." (PMID 36424447, 2022). "Whereas related alphaviruses, including Ross River virus (RRV), Semliki Forest virus (SFV), Sindbis virus (SINV) and Venezuelan equine encephalitis virus (VEEV), also depend on CD81 for infection, RNA viruses from other families, such as coronaviruses, replicate independently of CD81." (PMID 35612284, 2022). "Indeed, as the CD63, CD81, and CD9 expressions in HIV-1-infected T cells were enhanced for up to 24 h post infection, infectious exosomes displayed higher CD81 and CD9." (PMID 34769038, 2021). "Interestingly, the magnitude of the effect of AQP9 silencing in human hepatocytes on infection by P. falciparum, either on parasite entry or on the number of schizonts, is comparable to that of CD81 silencing." (PMID 34268141, 2021). "CD81 inhibition did not impede P. berghei infection of SR-B1-deficient hepatocytes, but, paradoxically, substantially increased the infection rate, similarly to WT hepatocytes." (PMID 32782257, 2020). "Cellular depletion of CD81 induced a weak infection rate inhibition of 25 to 30%." (PMID 30279342, 2018). "Besides, it efficiently blocked HCVpp (JFH1, genotype 2a; TH, genotype 1b) infection in 3D culture similarly to anti-CD81 mAb." (PMID 29682171, 2018). "This screen was designed for identification of genes that rendered the non-permissive CD81+ SR-BI+ HEK293T cell line susceptible to infection by HIV-luc reporter vector pseudotyped with HCVgp (HCVpp)." (PMID 28067225, 2017). "Here we demonstrate that CD81 and SR-BI define independent entry pathways for sporozoites, and identify the parasite protein P36 as a critical parasite factor that determines host receptor usage during hepatocyte infection." (PMID 28506360, 2017).
infection (continued). "It remains unknown if either protein makes contact with the sporozoite, although it has been suggested that SRB1 might directly engage the parasite, whereas CD81 indirectly impacts infection." (PMID 29201016, 2017). "Since CD81 downregulation was also observed during infection with UV-inactivated virus we hypothesized that this tetraspanin is part of the viral entry process." (PMID 29121670, 2017). "To investigate the potential for other TNF superfamily members to promote hepatocellular permissiveness to support HCV entry, we screened a panel of recombinant human TNF superfamily members for their effect on HCV pseudoparticle (HCVpp) infection of polarized HepG2.CD81 cells." (PMID 27983476, 2017). "As expected, anti-CD81 antibody also efficiently inhibited JFH1 infection of Huh7.5 cells." (PMID 29258547, 2017). "While CD81 alone is not sufficient for HCV entry, a recently published mouse model expressing known human entry receptors demonstrated that CD81 had to be co-expressed with occludin, scavenger receptor type B class I, and claudin 1 for optimal infection of murine hepatocytes." (PMID 29121670, 2017). "To further investigate the role of HCV entry factors, we evaluated whether infection of pancreatic islet cells was dependent on CD81 and/or SR-B1." (PMID 29258547, 2017). "Likewise, bead-based flow cytometric analysis also revealed that the release of CD63/CD81+ host cell MVs also increased upon infection." (PMID 29132302, 2017). "Interestingly, infection of cells with VSV, which is known to be infectious and pathogenic in humans, also led to the downregulation of CD9, CD81, CD151 and EGFR." (PMID 29121670, 2017). "In addition, infectious titers in the culture supernatants at 72 h post-infection exhibited little decrease in SR-KO cells, in contrast to the much greater decreases in CD81, CLDN1 or OCLN KO Huh7 cells." (PMID 27152966, 2016). "Finally, we validated the practical applications of our approach by re-examining the importance of host ligand CD81 for hepatocyte infection by P. falciparum sporozoites in vitro and assessment of the inhibitory activity of anti-sporozoite antibodies." (PMID 26070149, 2015). "It has been previously shown that functional antibody-based neutralization of CD81 on the surface of primary human hepatocytes abolishes infection by P. falciparum sporozoites in vitro as measured by the numbers of P. falciparum EEFs detected by immunofluorescence." (PMID 26070149, 2015). "Anti-CD81 and anti-SR-BI antibodies inhibited infection, confirming receptor-dependent virus entry." (PMID 25667327, 2015). "In addition to the four essential factors for HCV entry, CD81, SR-BI, claudin-1 and occludin, several additional factors facilitate infection." (PMID 25701818, 2015). "CD81 plays a critical role in an early step of normal primary human hepatocyte infection by HCV." (PMID 26214688, 2015). "We next tested CD81-deficient Huh7.25-CD81 cells and found that HCV exosomes could still mediate HCV transmission but infection rate with the free virus entry was significantly diminished." (PMID 25275643, 2014). "Although the affinity of E2 glycoprotein for CD81 may differ depending on viral genotype, anti-CD81 antibodies are able to block infection of HCV from different genotypes." (PMID 24509809, 2014). "Nevertheless, the prophylactic application of CD81-specific antibody may be exploited in liver transplantation to overcome re-infection of the graft, which remains an important challenge." (PMID 24553110, 2014). "Moreover, anti-human CD81 antibodies blocked infection of human hepatocytes by P. falciparum, the human pathogen." (PMID 24509809, 2014). "Moreover, CD81 is also involved in infection by many pathogens including parasites, bacteria, fungi and viruses." (PMID 24509809, 2014).
infection (continued). "In addition, in vivo studies showed that treatment with anti-CD81 antibodies prevented HCV infection when administrated before infection, but was unable to block HCV spread therapeutically soon after infection." (PMID 24509809, 2014). "Depletion of CD81 resulted in a substantial defect in viral fusion and infection." (PMID 24130495, 2013). "To this end, we developed a subcutaneous (s.c.)immunization protocol where few, possibly none, of the immunizing irradiated Plasmodium yoelii sporozoites infect hepatocytes, and also used CD81-deficient mice non-permissive to productive hepatocyte infections." (PMID 23255300, 2013). "Depleting CD81 led to a significant defect in viral uncoating and infection." (PMID 24130495, 2013). "Since cell polarization is accompanied by changes in the actin cytoskeleton and CD81 links to actin via its C-terminus, we studied the dynamics of a mutant CD81 lacking a C-terminal tail (CD81ΔC) and its effect(s) on HCVpp mobility and infection." (PMID 23126643, 2013). "A contribution of CD81 to infection of T cells by the patient-derived virus has also been shown." (PMID 23626783, 2013). "Therefore, the lower infection efficiency of HuH-7T1 was probably due to the reduced number of CD81-expressing cells." (PMID 23285155, 2012). "Lunet CD81/GFP-NLS-MAVS cells were used to determine infection of Con1 particles." (PMID 22558311, 2012). "JC1 control as well as serum infections were potently inhibited by anti-CD81 antibodies." (PMID 23300900, 2012). "Our observations suggest that HCV internalization might be rapid, whereas in vitro infection can be neutralized by anti-CD81 antibodies even 30 min after virus binding." (PMID 22039521, 2011). "Human CD81 alone was found to be required for J6JFH1 infection into all IRK and IPK cells tested." (PMID 21731692, 2011). "Because stochastic events can result in the formation of the requisite number of complexes, cells expressing few CD81 molecules have small but nonzero susceptibilities to infection." (PMID 22174670, 2011). "Indeed, ectopic expression of a TRIM25 P358L construct was as efficient as a TRIM25wt construct to increase IFN induction in the Huh7.25.CD81 cells, after infection with Sendai virus (SeV)." (PMID 22022264, 2011). "In these experiments, cells with high CD81 expression were preferentially infected and lost due to virus-induced cytopathicity, and cells with low CD81 expression, refractory to infection, eventually dominated the culture, suggesting that CD81 expression limited entry." (PMID 22174670, 2011). "Expression of human CD81 and occludin was essential for infection of genetically humanized mice." (PMID 22174670, 2011). "Above a certain, CD81 did not limit entry and cells were nearly completely susceptible to infection." (PMID 22174670, 2011). "In contrast, the M405T mutation stimulated infection through mouse CD81 without affecting entry via human CD81." (PMID 20617177, 2010). "Interestingly, L216F and V388G at the same time reduced efficiency of infection via the human CD81 counterpart." (PMID 20617177, 2010). "However, selectively Jc1/mCD81 has attained a higher efficiency of infection in cells displaying CD81 levels in excess of the minimal CD81 level." (PMID 20617177, 2010). "In our view, this finding lends further support to the notion that these mutations may facilitate receptor-dependent conformational changes of the glycoproteins thus permitting the use of mouse CD81 and ultimately infection of cells via solely mouse factors." (PMID 20617177, 2010). "Recently, another Huh7 subclone that could efficiently replicate the JFH1 subgenomic replicon (clone Huh7.25) was stably transfected with the essential HCV CD81 receptor, to generate Huh7.25/CD81 cells that are highly permissive to infection by JFH1." (PMID 20485506, 2010).